Y_RNA (Y RNA )
Gene: Miscellaneous RNA gene on chromosome 1 (37,737,955 to 37,738,054, reverse strand). Ensembl gene ENSG00000200421.
Homologues: Orthologues: chimpanzee Y_RNA (100% identical). Paralogues in human: Y_RNA (89% identical), Y_RNA (88% identical), RNY3P1 (87% identical), Y_RNA (87% identical), RNY3 (86% identical), RNY3P11 (86% identical), Y_RNA (86% identical), Y_RNA (85% identical), Y_RNA (84% identical), RNY3P14 (83% identical), Y_RNA (83% identical), RNY3P2 (82% identical), and 97 more.